TNFSF13B (TNF superfamily member 13b)
Diseases named in the same sentence as TNFSF13B in open-access papers (continued):
Sharing a sentence is not in itself a finding about the gene and the disease.
xerostomia (1 paper, 2022). Dryness of the mouth resulting from reduced salivary secretion. "TNFSF13B is another gene of interest related to xerostomia, as, in our analysis, it had the greatest drug–gene interaction score of 63.79 among drugs that have been/are being evaluated in clinical trials." (PMID 35268532, 2022). "The PPI network genes IL6R, EGFR, NFKB1, MPO, and TNFSF13B constitute a possible biomarker signature of xerostomia." (PMID 35268532, 2022). "The IL6R, EGFR, NFKB1, MPO, and TNFSF13B genes might all have implications in the diagnosis and intervention of xerostomia." (PMID 35268532, 2022). "Other genes that may be of interest in the development and treatment of xerostomia are MPO and TNFSF13B, both of which are involved in the significantly overrepresented GO ‘immune system process’ (GO:002376)." (PMID 35268532, 2022).
tumor (131 papers, 2006 to 2026). "Results revealed that high FAS, TNFRSF14, TNFRSF17, TNFRSF1B, and TNFSF13B expressions are associated with a high probability of “hot” tumor." (PMID 36588791, 2022). "Analysis of predicted MAC-MT interactions with other immune cells based on receptor-ligand expression using CellPhoneDB demonstrated that MAC-MT within tumor samples had increased expression of the gene encoding BAFF (TNFSF13B) with the potential to support BAFF-R-expressing B cells." (PMID 34936871, 2021). "But TNFSF13B enrichment in tumor samples, and patients with high TNFSF13B expression were correlated with tumor progression and poor prognosis." (PMID 37085921, 2023). "TNFSF13B, which enriched in tumor with hyperplastic blood vessels, was identified as a possible HOOK1‐associated protein." (PMID 37085921, 2023). "For example, CTLA4, STAC3, TBC1D10C and TNFSF13B were found to show weaker correlation with KIR (Killer Cell Immunoglobulin-like Receptor) family genes in tumor condition." (PMID 37908350, 2023). "We analyzed the gene expression levels of 12 hub genes with clinical tumor stages and found that TNFSF13B, CASP5 and GJB6 correlated positively with tumor stages, while FREM1 showed negative associations with tumor stages." (PMID 32311223, 2020). "Univariate Cox analysis showed that Age, Grade, Stage, T (T stage), N (Lymph node), M (Tumor metastasis), and TNFSF13B (p < 0.001) were prognostic factors, it has very significant statistical significance." (PMID 32655996, 2020). "It was found that HOOK1 overexpression could reduce the TNFSF13B transduced tumor burden and increased the sensitivity of RCC to sunitinib." (PMID 37085921, 2023). "However, we started from the tumor microenvironment, went through many aspects of screening, and finally selected the representative gene TNFSF13B." (PMID 32655996, 2020). "Our findings strongly suggest that TNFSF13B may be a potential biomarker or target related to the tumor microenvironment for KIRC." (PMID 32655996, 2020). "There is a positive correlation between TNFSF13B and tumor microenvironment." (PMID 32655996, 2020). "Further study of TNFSF13B may improve understanding of the potential relationships between the tumor microenvironment and the prognosis of KIRC." (PMID 32655996, 2020). "Interestingly, TNFSF13B and CASP5 proved to be risk signature in TCGA cohort and correlated with advanced tumor stages in GSE53757." (PMID 32311223, 2020). "The expression of TNFSF13B in tumor tissue is higher than that in normal tissue (p < 0.001)." (PMID 32655996, 2020). "POSTN, PPEF1, SAMSN1 and TNFSF13B were upregulated in a great majority of the ccRCC tumours." (PMID 27358011, 2016). "CD86, IL10RA, TNFSF13B, and CMKLR1 suppress effective anti-tumor immunity while simultaneously potentially promoting pro-tumor immune subsets – representing immunosuppressive signaling." (PMID 41006647, 2025). "The results showed a significant correlation between CHST11 and certain tumor immunostimulators (CD28, IL2RA, and TNFSF13B), tumor immunoinhibitors (CD96 and LGALS9), and MHC proteins (HLA-DRA and HLA-DMB)." (PMID 38565604, 2024). "Mechanistically, HOOK1 inhibited tumor growth and metastasis via canonical and non‐canonical TGF‐β pathway, and inhibited RCC angiogenesis and sunitinib resistance via TNFSF13B/VEGF‐A signaling." (PMID 37085921, 2023). "In the validation cohort from GSE53757, TNFSF13B, CASP5, and GJB6 correlated positively with tumor stages, while FREM1 negatively correlated with tumor stages." (PMID 32311223, 2020). "Through our research, TNFSF13B can not only predict the prognosis of KIRC, but also be an important medium for KIRC to transmit information between the tumor cell and tumor microenvironment, and is a potential therapeutic target." (PMID 32655996, 2020).
tumor (continued). "We next queried the relationship between TNFSF13B and immune cell infiltration in the TIMER database, and found that its expression was positively correlated with tumor purity and positively correlated with immune cells." (PMID 32655996, 2020). "APRIL/TNFSF13 and BAFF/TNFSF13B bind to the TACI/TNFSFR13B and BCMA/TNFSFR17 receptors, and play major roles in the recruitment, maturation, differentiation and survival of B cells, as well as the anti-tumor efficacy of DCs." (PMID 37435077, 2023). "When considering the opposite signaling, we observed an upregulation of Hc cytokine, tumor necrosis factor ligand superfamily member 13b (Tnfsf13b), and the anti-inflammatory cytokine IL-6 only in mice injected with USP7ATRT tumor cells and treated with three systemic injections of ZIKVBR." (PMID 34696533, 2021). "Importantly, we further observed that TNFSF13B, CASP5 and XCR1 showed the remarkable correlations with tumor‐infiltrating immune cells." (PMID 32311223, 2020). "The tumour microenvironment plays an important role in CLL, since neoplastic cells rely on survival factors such as B-cell activating factor (BAFF; TNFSF13B) and proliferation-inducing ligand (APRIL; TNFSF13), provided, inter alia, by non-neoplastic nurse like cells (NLCs)." (PMID 33036273, 2020). "Furthermore, TNFSF13B and CASP5 were proved to be correlated with advanced tumor stages in GSE53757." (PMID 32311223, 2020). "Upregulation of genes such as POSTN, TNFSF13B and SAMSN1 could provide increased metastatic potential of the tumour, as discussed." (PMID 27358011, 2016). "The augmented presence of immune ligand-receptor pairs such as IL-6, TNFSF13B, LGALS9-CD45, and HLA-E-KIR underscores the pivotal role of macrophages in modulating inflammatory responses, immune evasion, and reshaping the tumor microenvironment within the context of elevated LST1 expression." (PMID 41488617, 2025). "In contrast, the activity of pathways from macrophages, such as VEGFB to VEGFR1 and TNFSF13B to TNFRSF13B, was reduced in tumors, possibly reflecting adaptive changes in macrophage function under tumor conditions, which could impact immune responses and tumor cell regulation (right)." (PMID 39850883, 2024).
infection (94 papers, 2009 to 2026). The state of being infected such as from the introduction of a foreign agent such as serum, vaccine, antigenic substance or organism. "Cells within cluster 0, 1, 2, 3, and to a lesser extent cells within cluster 5 up-regulated genes associated with FRCs in response to infection, including Pdpn, Pdgfra, Pdgrfb, Vim, and Col6a3, as well as secreted factors such as Vefga and Tnfsf13b (encoding for BAFF)." (PMID 37983289, 2023). "Hence, copy number gains in CD8alpha and TNFSF13B in the 1978 and Ross308 lines may be linked to increased inflammation in response to infection." (PMID 31952471, 2020). "TNFSF13B promotes B-cell survival and proliferation, particularly during infection and immune responses." (PMID 41006647, 2025). "Further, we found increased expression of M1 macrophage markers Ccl8, Ido1, and Tnfsf13b in Stat2−/− mice during super-infection when compared to WT mice." (PMID 30337919, 2018). "Furthermore, the expression of Tnfsf13b was higher in microglia from infected mice, suggesting that this B cell pro-survival factor is induced upon infection." (PMID 36180478, 2022). "The CXCL9, CXCL10, CXCL11/CXCR3 axis and TNFSF13B play a role in both these recruitment and activation processes, responsible for attracting Th1 cells, cytotoxic lymphocytes and natural killer cells to the site of the infection, and related to B-cell activation, respectively." (PMID 34276658, 2021). "DC isolated early after infection of pigs with either of the two CSFV strains showed prominent upregulation of CCL5, CXCL9, CXCL10, CXCL11, and XCL1, as well as of the cytokines TNFSF13B, IL6, IL7, IL12B, IL15, IL27." (PMID 32733474, 2020). "For example, TNFSF13B, FOS, POLR3G and PRKCE were down-regulated at 3 h post infection, while ITGB7 and THBD were up-regulated." (PMID 28938587, 2017). "TNFSF13B contributes to the activation, proliferation, and differentiation of B lymphocytes, while TNFSF18 regulates the activation of monocytes and T lymphocytes in the immune response against pathogen infection." (PMID 38847223, 2024). "We detected at day 3pi an upregulation in the expression of CD19, the B cell receptor co-receptor, as well as B-cell activating factor (BAFF/TNFSF13B), a potent B cell activator, which indicates that B cells could be activated early in the infection." (PMID 37920474, 2023). "In this study, TNFSF13B mRNA expression was highly significantly elevated in PBMC from N'Dama at 14 dpi (4.7-fold, P = 0.0008) and significantly increased at 21 dpi (2.0-fold, P = 0.0169) relative to pre-infection levels." (PMID 19409086, 2009).
cancer (69 papers, 2008 to 2026). A tumor composed of atypical neoplastic, often pleomorphic cells that invade other tissues. "Consistent with the cancer hallmark analysis, TNF (TNFSF13B), TGFB1, and TGFB3 played important roles in the mesenchymal microenvironment crosstalk." (PMID 37370765, 2023). "Of those modulated genes, SPP1, IL1RN, IL1A, TNFSF13B, OSM, and CSF3 had the most clinical relevance, as their high expression was associated with poor cancer patient overall survival." (PMID 31022845, 2019). "Cancer cells modulate the expression and secretion of several anti-proliferative molecules on DBMSCs, including, CD40LG, CXCL9, IL9R, IL-15, TNFSF13B, IL-9, IL-17, and CXCL1." (PMID 39768220, 2024). "In various types of cancer, findings between NNMT and immunostimulator gene expression showed a high connection (p < 0.05), including TNFSF13B, TNFRSF8, TNFSF14, IL6, IL2RA, CD80, CD27, and CD86." (PMID 36386816, 2022). "In solid tumors, TNFSF13B expression varies among different cancer types, and its prognostic and functional roles are not well understood." (PMID 39235457, 2024). "Taken together, the APRIL/TNFSF13, BAFF/TNFSF13B, and MMP-3 pathway plays a critical role in the regulation of the immune system, and dysregulation of this pathway can lead to the development of cancer." (PMID 37511338, 2023). "Considering the downregulation of antimicrobial humoral response in cancer, we supposed the two B cell immuno‐stimulators, CD48 and TNFSF13B, could be the potential targets as well." (PMID 33694292, 2021). "Our group has focused on two members of this superfamily, whose role in cancer is less well-defined, namely APRIL (A PRoliferation Inducing Ligand, TNFSF13) and BAFF (B-cell Activating Factor of the TNF Family, also known as B Lymphocyte Stimulator (BLyS), TNFSF13B)." (PMID 30131941, 2018). "Studies have shown that human infant TNFSF13B is the most demethylated gene in the TNFSF family, with a 20% decrease in β after birth; STAT2 plays an important role in the immune response to intracellular and extracellular stimuli, including in inflammation, foreign substance invasion, and cancer." (PMID 39202427, 2024). "Since the functions of B cells in cancer immunity are not as well understood as those of T cells, further investigation is needed to determine whether TNFSF13B regulates PD-L1 expression in NSCLC." (PMID 39235457, 2024).
inflammatory myopathies (3 papers, 2018 to 2025). "Several tumor necrosis factor (TNF) superfamily genes (TNFSF8, LTB, TNFSF12, TNFSF13B, TNFSF14, TNFSF13, EDA) were upregulated, with LTB and EDA reaching higher levels than in other inflammatory myopathies." (PMID 41441888, 2025).
metabolic disease (3 papers, 2016 to 2022). A congenital disorder (due to inherited enzyme abnormality) or acquired (due to failure of a metabolically important organ) disorder resulting from an abnormal metabolic process. "Thirdly, the exact mechanisms of metabolic disorders mediated by TNFSF13B and OAS1 and their exact relationship with monocytes need further investigation." (PMID 36341378, 2022).
neurodegenerative disease (3 papers, 2013 to 2023). A disorder of the central nervous system characterized by gradual and progressive loss of neural tissue and neurologic function. "Collectively, these findings suggest that TNFSF13B may have a neuroprotective effect in neurodegenerative diseases, but further investigations are required to confirm this hypothesis." (PMID 37649719, 2023).
blood cancers (2 papers, 2013 to 2024). "Among the proteins associated with risk of haematological cancers, we identified associations with risk of multiple blood cancers for members of the FC-receptor protein [FCRL1, FCRL2, FCRL3, FCRL5, FCRLB] and TNF receptor families [TNFRSF4, TNFRSF9, TNFRSF13B, TNFRSF13C, TNFSF13B, TNFSF13]." (PMID 38750076, 2024).
TNFSF13B also shares sentences with these, for which no sentence is quoted: multiple myeloma (35 papers); B-cell lymphomas (24); systemic sclerosis (23); IgA nephropathy (22); sarcoidosis (18); chronic lymphocytic leukemia (17); pulmonary fibrosis (17); malaria (16); nephritis (15); Insulin resistance (14); kidney disease (13); lymphopenia (13); asthma (12); hematological malignancies (12); leukemia (12); chronic GVHD (11); Graves disease (11); kidney transplant (11); Sepsis (11); HIV-1 infection (10); scleroderma (10); acute lymphoblastic leukemia (9); AIDS (9); B cell deficiency (9); bacterial infections (9); interstitial lung disease (9); myositis (9); chronic obstructive pulmonary disease (8); common variable immunodeficiency (8); myocardial infarction (8).
A further 334 diseases each share a sentence with TNFSF13B in 8 papers or fewer.